PUM1 (pumilio RNA binding family member 1)
Description:
Sequence-specific RNA-binding protein that acts as a post-transcriptional repressor by binding the 3'-UTR of mRNA targets. Binds to an RNA consensus sequence, the Pumilio Response Element (PRE), 5'-UGUANAUA-3', that is related to the Nanos Response Element (NRE). Mediates post-transcriptional repression of transcripts via different mechanisms: acts via direct recruitment of the CCR4-POP2-NOT deadenylase leading to translational inhibition and mRNA degradation. Also mediates deadenylation-independent repression by promoting accessibility of miRNAs. Following growth factor stimulation, phosphorylated and binds to the 3'-UTR of CDKN1B/p27 mRNA, inducing a local conformational change that exposes miRNA-binding sites, promoting association of miR-221 and miR-222, efficient suppression of CDKN1B/p27 expression, and rapid entry to the cell cycle. Acts as a post-transcriptional repressor of E2F3 mRNAs by binding to its 3'-UTR and facilitating miRNA regulation. Represses a program of genes necessary to maintain genomic stability such as key mitotic, DNA repair and DNA replication factors. Its ability to repress those target mRNAs is regulated by the lncRNA NORAD (non-coding RNA activated by DNA damage) which, due to its high abundance and multitude of PUMILIO binding sites, is able to sequester a significant fraction of PUM1 and PUM2 in the cytoplasm. Involved in neuronal functions by regulating ATXN1 mRNA levels: acts by binding to the 3'-UTR of ATXN1 transcripts, leading to their down-regulation independently of the miRNA machinery. Plays a role in cytoplasmic sensing of viral infection. Involved in embryonic stem cell renewal by facilitating the exit from the ground state: acts by targeting mRNAs coding for naive pluripotency transcription factors and accelerates their down-regulation at the onset of differentiation (By similarity). Binds specifically to miRNA MIR199A precursor, with PUM2, regulates miRNA MIR199A expression at a postranscriptional level.
Synonyms: HsPUM; KIAA0099; PUMH1; NEDMSF; PUMH; PUML1; SCA47
Tractability: PROTAC: ubiquitination databases record sites on it; its protein half-life has been measured.
Gene: Protein-coding gene on chromosome 1 (30,931,505 to 31,065,991, reverse strand). Ensembl gene ENSG00000134644.
Subcellular location: Cytoplasm; Cytoplasm, P-body; Cytoplasmic granule
Subcellular location (Human Protein Atlas): Cytosol; Nucleoplasm
Pathways (Reactome):
Vesicle-mediated transport: Golgi Associated Vesicle Biogenesis
Gene Ontology:
Molecular function: miRNA binding; mRNA 3'-UTR binding; protein binding; RNA binding
Biological process: miRNA processing; positive regulation of miRNA-mediated gene silencing; positive regulation of RIG-I signaling pathway; post-transcriptional regulation of gene expression; regulation of cell cycle; regulation of chromosome segregation; regulation of mRNA stability; 3'-UTR-mediated mRNA destabilization; adult locomotory behavior; mRNA destabilization; post-transcriptional gene silencing; regulation of miRNA-mediated gene silencing; spermatogenesis; stem cell differentiation
Cellular component: cytoplasmic stress granule; cytosol; nucleoplasm; P-body; axon; cytoplasm
Genetic constraint (gnomAD): Loss-of-function variants: 13 observed, 124.92 expected, observed/expected ratio (o/e) 0.1, 90% interval 0.067 to 0.17. The upper end of that interval is the gene's LOEUF score, 0.17, which puts it in group 1 of 6, group 1 being the genes least tolerant of losing a copy. Missense variants: 926 observed, 1,523.7 expected, observed/expected ratio (o/e) 0.61, 90% interval 0.57 to 0.64. Synonymous variants: 496 observed, 565.28 expected, observed/expected ratio (o/e) 0.88, 90% interval 0.81 to 0.94.
Homologues: Orthologues: chimpanzee PUM1 (100% identical), macaque PUM1 (100% identical), pig PUM1 (99% identical), dog PUM1 (99% identical), guinea pig PUM1 (99% identical), mouse Pum1 (99% identical), rat Pum1 (99% identical), rabbit PUM1 (99% identical), tropical clawed frog pum1 (91% identical), zebrafish pum1 (81% identical), Drosophila melanogaster pum (44% identical), Caenorhabditis elegans puf-9 (26% identical), and 7 more. Paralogues in human: PUM2 (70% identical).
Diseases named in the same sentence as PUM1 in open-access papers:
PUM1 is named in the same sentence as 68 diseases in open-access papers, as found by Europe PMC text mining. Sharing a sentence is not in itself a finding about the gene and the disease. The quoted sentences say what the papers report.
breast carcinoma (14 papers, 2007 to 2026). "A previous study indicated that PUM1 is among the key genes in BC, where PUM1 has been associated with the regulation of carcinogenesis via the PUM1/eIF2 axis by interacting with long non-coding RNAs in breast cancer." (PMID 41155797, 2025). "Subsequent study should investigate the correlations between PUM1, and additional molecular pathways involved in breast cancer progression." (PMID 41155797, 2025). "For example, miR-323a-3p inhibits ErbB4 and affects depression, inhibits UHMK1 to down-regulate tumor growth in colorectal cancer, and inhibits PUM1/eIF2 axis in breast cancer." (PMID 35319011, 2022). "Based on the results of the present study, we suggest the use of HSP90AB1, DAD1, PFN1 and PUM1 in any combination of threes (triplet) for normalization of the expression of genes of interest in SK-BR-3 breast cancer cell line." (PMID 34681026, 2021). "Our results indicate cfDNA regions of PUM1 and RNAse P genes as able to distinguish between early‐stage breast cancer patients and healthy women in a Peruvian cohort." (PMID 33522650, 2021). "Among other RBPs such as Elav-like (Elavl) proteins, Staufen1, and RNA binding protein fox-1 homolog 2 (Rbfox2), we found the Pumilio protein family consisting of Pum1 and Pum2 to be highly expressed in glioblastoma, neuroblastoma, and breast cancer cells." (PMID 34445704, 2021). "We focus on the application of highly sensitive technology such as digital PCR (dPCR) to differentiate breast cancer (BC) patients and controls by quantifying regions of PUM1 and RPPH1 (RNase P) in plasma samples." (PMID 33522650, 2021). "In a case-control study, breast cancer patients had a higher number of cfDNA copies of PUM1 and RNaseP genes detected in peripheral blood compared with healthy controls." (PMID 30792813, 2019). "The findings of this study indicate that PUM1 may serve as a potential prognostic biomarker in breast cancer." (PMID 41155797, 2025). "Because the knockdown of PUM1 reduced the number of cells in S phase and inhibit cell proliferation, the authors suggested that PUM1 may promote tumorigenesis in breast cancer." (PMID 35338151, 2022). "The median count for PUM1 was 4.6 copies/μL (standard deviation [SD]: 1.96) versus 10.6 copies/μL (SD: 3.82) and for RNaseP, 3.2 copies/μL (SD:1.57) versus 7.6 copies/μL (SD:3.45) for healthy controls versus breast cancer patients, respectively (p <0.0001 in both cases)." (PMID 30792813, 2019). "Researchers have also used multiplex ddPCR to detect common gene indicators in breast cancer, achieving highly consistent results with immunohistochemistry (IHC) detection by simultaneously detecting HER2, ESR1, PUM1, and PGR genes." (PMID 40042093, 2025). "When examining the 18 patient tissue specimens (ER+/ER- IBC/normal) or the breast cancer tissue specimens alone (ER+/ER- IBC), the 3-gene combination of RPLP0, TBP and PUM1 were consistently identified by geNorm to exhibit the highest degree of stability." (PMID 18211679, 2008).
Ataxia (11 papers, 2018 to 2025). Ataxia refers to impaired coordination of voluntary muscle movement. "The present study includes a family (Family 407 L) previously reported to carry a potential disease‐causing variant in PUM1 (Family X; NM_001020658.2: c.3103A>T (p.Thr1035Ser)) associated with the adult‐onset ataxia segregating in a multi‐generational family." (PMID 40191983, 2025). "In the recent 3 years, subjects with Pumilio1-associated developmental disability, ataxia, and seizure syndrome have been identified as harboring Pumilio homolog 1 (PUM1) mutations." (PMID 35386260, 2022). "The mildest variant (T1035S), which reduces PUM1 levels by only 25%, causes a slowly progressive, pure ataxia with onset in the later decades of life, whereas the most severe missense mutation (R1147W) reduces PUM1 levels by ~ 50% and causes a severe developmental syndrome." (PMID 37070548, 2023). "Although there is no obvious ortholog of Puf3 in mammalian organisms, PUM1 and PUM2 are mammalian Pumilio proteins whose disruption have been associated with ataxia or mitochondrial phenotypes." (PMID 37216416, 2023).
colon cancer (8 papers, 2021 to 2025). "Notably, PUM1 has been implicated in the progression of various cancers, including non-small cell lung, ovarian, prostate, and colon cancer." (PMID 37624174, 2023). "In colon cancer, higher PUM1 expression has been observed in tumor tissues and cell lines, and overexpression of PUM1 significantly promoted cell proliferation, colony formation, cell migration, and colonosphere formation." (PMID 37624174, 2023). "Dolasetron and ketoprofen demonstrate promise as effective anti-cancer and anti-cancer stem cell drugs, inducing apoptosis in colon cancer cells through inhibition of PUM1." (PMID 37624174, 2023). "The repurposing of dolasetron and ketoprofen as potential therapeutic agents targeting PUM1 represents a promising avenue for intervention in colon cancer treatment." (PMID 37624174, 2023). "For instance, targeting PUM1 using siRNA-encapsulated nanoparticles reduced colorectal tumor growth in a murine orthotopic colon cancer model." (PMID 37624174, 2023). "In conclusion, this study highlights the potential of targeting PUM1 as a novel approach to colon cancer treatment." (PMID 37624174, 2023). "Our findings show the potential of dolasetron and ketoprofen in inducing cytotoxicity in colon cancer and cancer stem cells by targeting PUM1." (PMID 37624174, 2023). "To further investigate PUM1’s influence on the proliferation of drug-resistant colon cancer cells treated with cetuximab, we performed PUM1 knockout experiments using CRISPR-Cas9 carrying PUM1 sgRNA." (PMID 34447749, 2021). "These experiments clearly demonstrated that PUM1 positively regulated DDX5 in cetuximab-resistant colon cancer cells." (PMID 34447749, 2021). "Additionally, the plant flavonoid morin has been found to inhibit colon cancer stem cells in vitro by suppressing PUM1 expression." (PMID 37624174, 2023). "Furthermore, immunofluorescence was performed with PUM1 and some colon cancer stems markers such as DCLK1 and CD133." (PMID 37624174, 2023). "Furthermore, intravenous injection of nanoparticle-encapsulated anti-Pum1 and Pum2 siRNAs reduces colorectal tumor growth in murine orthotopic colon cancer models." (PMID 35338151, 2022). "Drug treatment also reduced PUM1 expression and cancer stem cell marker (DCLK1 and CD133) expression in colon cancer cells." (PMID 37624174, 2023). "Our study suggests that PUM1 positively regulates DDX5 and acts as a promoter in cetuximab-resistant colon cancer cells." (PMID 34447749, 2021). "We established cetuximab-resistant colon cancer cell lines SW480R and Caco-2R and knocked out PUM1 and DEAD-box helicase 5 (DDX5) with the clustered regularly interspaced short palindromic repeats (CRISPR)-caspase 9 (Cas9) system." (PMID 34447749, 2021). "In this study, we found that PUM1 was upregulated in the established cetuximab-resistant colon cancer cell lines SW480R and Caco-2R compared with their parent cell lines, which implies that PUM1 is involved in promoting acquired cetuximab resistance." (PMID 34447749, 2021). "Thus, we established cetuximab-resistant colon cancer cell lines SW480WR and Caco-2R and investigated the mechanism of action of PUM1 in those cells." (PMID 34447749, 2021). "Hence, morin downregulates both Pumilio-1 (PUM1) and CD133, leading to inhibition of Cancer Stem Cells (CSCs) that may remain after colon cancer treatment." (PMID 41515938, 2025). "It was also found that PUM1 can positively regulate (DDX5) and increase cell viability, thus proving that the downregulation of PUM1 and DDX5 can reduce tumor cell viability and is a therapeutic target for the increased sensitivity of colon cancer to trastuzumab." (PMID 37020597, 2023).
ovarian carcinoma (8 papers, 2019 to 2025). A malignant neoplasm originating from the surface ovarian epithelium. "It was recently discovered to play a role in the development of various cancers, such as ovarian cancer, pancreatic cancer, and leukemia, in which PUM1 acted as a tumor promoter." (PMID 34447749, 2021). "The PUM1 gene has been confirmed to be closely related to tumorigenesis and progression of ovarian cancer." (PMID 31751911, 2019). "In our previous study, we showed that the PUM1 gene was closely related with tumorigenesis and progression in ovarian cancer." (PMID 31751911, 2019). "The PUM1 gene is highly expressed in ovarian cancer tissues and closely related with ovarian cancer cell proliferation, migration, and invasion ability." (PMID 31751911, 2019). "After interfering with the expression of PUM1 in the A2780 ovarian cancer cell line, cell proliferation, migration, and invasion ability were inhibited, while cell apoptosis increased." (PMID 31751911, 2019). "Pumilio RNA-binding family member 1 (PUM1) has been reported to function as an oncogene in ovarian cancer and nonsmall cell lung cancer." (PMID 31395860, 2019). "Moreover, some authors reported that PUM1 promotes ovarian cancer proliferation, migration, and invasion." (PMID 30881377, 2019). "For the two ovarian cancer samples, dpCNV gets 225 cytobands and 128 cytobands, 285 genes and 529 genes overlapped with the COSMIC database, respectively, in which there are many important tumor driver genes corresponding to ovarian cancer, such as PUM1, GOLPH3L, PIWIL4, and KNDC1." (PMID 33519925, 2020).
pancreatic cancer (8 papers, 2019 to 2026). "Abnormal expression or dysfunction of PUM1 is associated with various disorders, including excess inflammation, malignant tumors (such as gastric cancer, colorectal cancer, and pancreatic cancer), and neurological diseases." (PMID 40689527, 2025). "High PUM1 expression has been associated with poor prognosis in patients with pancreatic cancer." (PMID 41155797, 2025). "Our previous studies showed that Pumilio RNA-binding family member 1 (PUM1) gene is abnormally expressed in pancreatic cancer (PC) tissues, and its knockdown suppresses the growth and metastasis of PC cells." (PMID 39296516, 2022). "Therefore, it is necessary to further discuss the role of PUM1 in the development of pancreatic cancer." (PMID 31395860, 2019). "Here, we aimed to evaluate the relationship between PUM1 protein levels and clinical characteristics of pancreatic ductal adenocarcinoma (PDAC) patients, the most common form of pancreatic cancer, accounting for ~85% of the cases." (PMID 31395860, 2019). "However, there is no information regarding the function of PUM1 in pancreatic cancer, and the role of PUM1 in regulating carcinogenesis has not been fully elucidated." (PMID 31395860, 2019).
colorectal cancer (6 papers, 2020 to 2025). A primary or metastatic malignant neoplasm that affects the colon or rectum. "In colorectal cancer, in silico analysis using the Human Protein Atlas and Cancer Genome Atlas revealed elevated levels of both PUM1 protein and mRNA transcripts." (PMID 38328550, 2024). "PUM1 is a key regulator for the initiation and progression of colorectal cancer." (PMID 38328550, 2024). "Here, we report that Pum1 and Pum2 display increased expression in human colorectal cancer (CRC)." (PMID 35338151, 2022). "For example, it has recently been demonstrated that in human colorectal cancer (CRC), Pum1 and Pum2 are expressed at elevated levels and that the knockdown by siRNA of Pum1 and Pum2 in a mouse model of CRC inhibits tumour progression." (PMID 37747106, 2023). "According to Bestkeeper software version 1, the most stable and suitable housekeeping genes across our colorectal cancer samples are GAPDH 2 (HGK 1) with standard deviation 0.71 and p = 0.01, PUM1 2 (HGK 2), and RPN1 (HGK 3) are equally good and have the same standard deviations 0.94 and p=0.001." (PMID 33457124, 2020).
endometrial cancer (6 papers, 2019 to 2025). Primary or metastatic malignant neoplasm involving the endometrium (mucous membrane that lines the endometrial cavity). "Circ_0000043 (circ_PUM1) is an example of circRNAs contributing to the progression of endometrial cancer through regulation of NOTCH 3 expression." (PMID 40761890, 2025). "CircTNFRSF21, circ_0000043, hsa_circ_0061140, hsa_circ_0002577, and circ_PUM1 were all elevated in endometrial carcinoma and facilitate the development of endometrial carcinoma by targeting different functional axes." (PMID 35130798, 2022). "Opposite results were observed with circ_PUM1 knockdown, and the tumorigenic ability of endometrial cancer cells after circ_PUM1 knockdown was reduced compared to control cells." (PMID 32073729, 2020). "To further investigate the role of circ_PUM1 in endometrial cancer, we examined its expression in HEC‐1B, and Ishikawa cells, and found that it was most highly expressed in HEC‐1B and least abundant in Ishikawa cells." (PMID 32073729, 2020). "The expression of circ_PUM1 was detected by qRT‐PCR in 16 normal endometrium and 69 endometrial cancer tissues." (PMID 32073729, 2020). "Circ_PUM1 was expressed at significantly higher levels in endometrial cancer tissues than in normal tissues." (PMID 32073729, 2020). "This research aimed to explore the role of circRNA PUM1 in the development and progression of endometrial cancer." (PMID 32073729, 2020). "In conclusion, our data suggest that circ_PUM1 plays a critical role in the development and progression of endometrial cancer, mainly by adsorbing miR‐136 via a ‘sponge’ effect and thereby promoting expression of the target gene NOTCH3." (PMID 32073729, 2020). "Together, these data suggest that circ_PUM1 promotes the development of endometrial carcinoma by targeting protein NOTCH3 via miR‐136." (PMID 32073729, 2020). "We detected the expression of circ_PUM1 by qRT‐PCR in 16 normal endometrial tissues and 69 endometrial carcinoma tissues." (PMID 32073729, 2020). "Here, we define the role and molecular mechanism of circ_0000043 (hereafter referred to as circ_PUM1) in the development and progression of endometrial carcinoma." (PMID 32073729, 2020). "Up‐regulation of circ_PUM1 promoted the proliferation, migration and invasion of endometrial carcinoma cells." (PMID 32073729, 2020). "Together, these data suggest that circ_PUM1 plays a role in the development of endometrial cancer." (PMID 32073729, 2020). "However, PUM1 is identified as one of the most stably expressed genes in uterine cervical cancer, endometrial carcinoma, gallbladder, leiomyoma, breast, and non-small cell lung cancers." (PMID 30881377, 2019). "Circ_PUM1 can compete with miR‐136, leading to up‐regulation of NOTCH3, and thereby promote the development of endometrial cancer." (PMID 32073729, 2020). "PSMC4, PUM1 and IPO8 were identified as the best reference genes combination for type 1 endometrial cancer (grades 1, 2 and 3), whereas for type 2 endometrial cancer (serous and carcinosarcoma), UBC, MRPL19, PGK1 and PPIA were the best reference genes combination." (PMID 32439920, 2020).